CRP (C-reactive protein)
Diseases named in the same sentence as CRP in open-access papers (continued):
Sharing a sentence is not in itself a finding about the gene and the disease.
infection (continued). "Elevated CRP levels in serum of SLE patients have been studied as a marker of disease activity versus the presence of coexistent infection." (PMID 26798529, 2015). "C-reactive protein and core temperature increased significantly with increasing likelihoods of infection, in contrast to leukocyte counts." (PMID 26346055, 2015). "C-reactive protein is an acute-phase-reactant synthesized by hepatocytes and an exquisitely sensitive systemic marker of tissue damage, tissue ischemia, infection, and inflammation." (PMID 26445912, 2015). "A rise in CRP level in acute-phase reactants has been successfully used as a marker of infection after surgical procedures." (PMID 25888882, 2015). "Comme attendu, le pourcentage des patients présentant une infection était également plus élevé chez les patients ayant un taux de CRP > 10 mg/L que chez ceux ayant un taux de CRP <10mg/L." (PMID 26301005, 2015). "The analysis revealed that IL-10 at 6 h, CRP at 6 h and NIHSS on admission are independently associated with infection (IL-10: P = 0.009; CRP: P = 0.018; NIHSS: P = 0.041)." (PMID 25613713, 2015). "C-reactive protein (CRP) is an acute phase protein that is stimulated by infection and CRP levels rise during pregnancy." (PMID 25806032, 2015). "Low-grade infection represents a challenge for the treating surgeon, as laboratory markers (such as C-Reactive Protein, erythrocyte sedimentation rate, white blood count) and conventional cultures of intra-operative samples can be negative 37,38." (PMID 25726940, 2015). "Another report showed that a second rise or failure to achieve a decrease in postoperative CRP values had good sensitivity and a good predictive value for postoperative infections." (PMID 25888882, 2015). "Uncontested of these risks of bias, persistently high or increasing concentrations of CRP have been suggested to indicate an ongoing inflammatory process, e.g., as a result of infection of the surgical wound." (PMID 26483038, 2015). "Increased plasmatic levels of CRP, IL-1, and procalcitonin, as well as observable symptoms, suggest infection development." (PMID 26413536, 2015). "In univariate analyses, the infection groups significantly differed in their exacerbation rate, clinical scores and CRP levels." (PMID 26093634, 2015). "Le pourcentage de patients présentant une infection est plus élevé chez les patients ayant un taux sérique de CRP > 10mg/L comparé à ceux ayant un taux sérique < 10 mg/L." (PMID 26301005, 2015). "CRP was a significant indicator of infection in hospitalized cirrhotic patients and a NLR was a useful predictor of 1-month survival, particularly in Child–Pugh class C patients." (PMID 26498833, 2015). "Associations were attenuated with adjustment for CRP and AGP, which suggests that infection or inflammation were related to this relationship, either as confounding or mediating factors." (PMID 26694646, 2015). "To exclude any effects introduced by infection or inflammation on IgG4 levels in this study, we further examined potential correlations between IgG4 with C-reactive protein (CRP) and white blood cell count (WBC)." (PMID 26451312, 2015). "As an acute phase reactant, CRP production increases in response to a variety of systemic events such as infection, trauma, or autoimmune inflammatory diseases." (PMID 25887518, 2015). "As a positive acute-phase protein, CRP would be increased obviously in the conditions of acute trauma, inflammation or infection." (PMID 26557421, 2015). "We note also that the attending physicians took the CRP values into consideration when retrospectively assessing infection likelihood." (PMID 26645559, 2015). "In conclusion, CRP and NLR are helpful diagnostic markers of infection in hospitalized cirrhotic patients." (PMID 26498833, 2015). "For diagnose of the infection, baseline CRP concentration was a significant factor compared to the presence of SIRS (odds ratio 1.202, P = 0.003)." (PMID 26498833, 2015).
infection (continued). "SLE patients with flare-up had significantly higher serum anti-dsDNA and E-C4d levels and lower CRP levels than those with infection." (PMID 26273660, 2015). "Widely used infection markers such as leukocyte count, procalcitonin, sedimentation rate and CRP were used." (PMID 28913037, 2015). "The positive APP include C-reactive protein (CRP) which plays important roles in protection against infection, clearance of damaged tissue, prevention of auto-immunization and regulation of the inflammatory response." (PMID 25888870, 2015). "Rapid increase in CRP synthesis within hours after infection suggests its contribution to host defense as part of the innate immune response." (PMID 26346216, 2015). "They found CRP to be of lower sensitivity for diagnosis of infection, but of increased sensitivity and specificity when measured 24 and 48 hours after diagnosis." (PMID 25894336, 2015). "GM-CSF treatment also increased the postoperative leukocyte counts while other markers of inflammation and infection such as temperature, CRP, PCT and IL-6 remained unaffected." (PMID 26641243, 2015). "There is generally a delay of up to 24 hours between the onset of symptoms of infection and rise in serum CRP." (PMID 26150837, 2015). "Bacterial infection is a potent stimulus of marked CRP elevation, which occurs within 4–6 h of infection and peaks after 36 h." (PMID 26672961, 2015). "Proteins that are routinely used to support diagnosis of infection include procalcitonin, C-reactive protein (CRP), and Interleukin-6 (IL-6)." (PMID 25785720, 2015). "In the present study, CRP level was an independent predictor of infection compared to the SIRS and MELD scores." (PMID 26498833, 2015). "Lower baseline CRP concentrations and a lower CRP response to infection have been suggested in case of preterm compared to term neonates." (PMID 25685774, 2015). "Mean CRP in patients with THA infection was about 98.2 mg/l (min/max 0.89–438 mg/l) and mg/l 117.5 (1.12–515 mg/l) in patients with TKA infection." (PMID 25987902, 2015). "CRP secretion by the liver is stimulated by several inflammatory cytokines, which are released in response to trauma, infection and inflammation, and this protein rapidly reduces the resolution of these conditions." (PMID 26264971, 2015). "ESR and CRP levels remain the first-line investigation, even though the sensitivity of their results is often diminished in low-grade infections." (PMID 24821631, 2015). "Several authors have tried to assess the value of maximum CRP levels and various established threshold levels, in diagnosing postoperative infection during arthroplasty." (PMID 25910083, 2015). "C-reactive protein (CRP) is a serological parameter conventionally used to distinguish SLE flare-up from infection." (PMID 26273660, 2015). "In the present case, the infection had deeply penetrated the site and the CRP level was 12.5 mg/dL before the start of linezolid administration." (PMID 26602090, 2015). "The median endocan level decreased by only 23% during infection, whereas both serum CRP and PCT levels decreased by more than 80%." (PMID 25894539, 2015). "CRP is a member of the pentraxin protein family, which is composed of five 23-kDa subunits and it can increase by 1,000-fold or more with infection, inflammation, and tissue injury." (PMID 25889630, 2015). "The first characteristic of endocan identified in the present study was that changes in serum levels during infection were smaller than those of CRP or PCT." (PMID 25894539, 2015). "In patients with infection, levels remained elevated until 24 h in the case of IL-10 and until day 7 in the case of IL-6 and CRP, respectively." (PMID 25613713, 2015). "CRP was helpful for the evaluation of the course of an infection and for monitoring the efficacy of antibiotic therapy." (PMID 25894336, 2015).
infection (continued). "Increased levels of inflammatory cytokines such as CRP represent an inflammatory response secondary to tissue damage induced by infection, trauma, and tumor necrosis." (PMID 26390126, 2015). "In the animal model indomethacin and infection caused a poor clinical state, a great number of reisolated bacteria, elevated white blood cell (WBC) count, decreased C-reactive protein (CRP) and serum albumin levels." (PMID 25001579, 2014). "The presence of abnormally high CRP levels on admission and clinical features of infection are highly suggestive of infected PG and require a combination of intravenous broad-spectrum antibiotics and immunosuppression." (PMID 25374597, 2014). "In our patient, fever, abdominal pain, leukocytosis, elevation of ESR and CRP gave rise to suspicion of infection." (PMID 25100894, 2014). "Additional acute phase reactants relevant to infection and endotoxemia include: C-reactive protein, clotting factors, hepcidin and complement that participates in bacterial opsonization." (PMID 24691127, 2014). "C-reactive protein was elevated over baseline in all patients, but subtly more so in those with verified infection." (PMID 24642872, 2014). "In our symptomatic joint arthroplasty patients, the posttest probability of infection was 96% when both PMNs and CRP level were positive." (PMID 25025886, 2014). "Serological analyses showed elevated mean serum levels of IL-6, IL-1β, and CRP in the MRSA-infected animals during the early phases of infection." (PMID 25184249, 2014). "On day 46 after intervention, fever (38.5°C) and oliguria abruptly developed, with local signs of infection: blood tests showed an increase of CRP (206 mg/L), serum creatinine (2.2 mg/dL), and leukocytes count (15.220/mm3)." (PMID 25374744, 2014). "In our animal study, the WBC counts, neutrophils, CRP in peripheral blood samples and exudate colonies reached maximum on Day 4 after infection and decreased significantly on Day 9 after antibiotics therapy in treatment groups." (PMID 25551618, 2014). "CRP levels increase rapidly up to 1000-fold during exposure to various inflammatory stimuli, and CRP is used routinely as a marker of infection often with a cut-off of 10 mg/L." (PMID 24516611, 2014). "CRP is an acute phase protein produced by the liver in response to various conditions, such as inflammation, infection, and malignancy." (PMID 24612599, 2014). "Laboratory data show low or marginally raised levels of white blood cells and C-reactive protein, reflecting, respectively, the subacute or acute character of the infection." (PMID 25386377, 2014). "In the study population as a whole blood CD3+ T cells at infection correlated inversely with peak serum C-reactive protein (CRP) (P = 0.045, r = −0.42), peak blood total leukocytes (P = 0.047, r = −0.42)." (PMID 24099891, 2014). "IL-6 is a cytokine that shows early response to infection, preceding the increase in C-reactive protein and followed by TNF-α release." (PMID 25614712, 2014). "In different infections and clinical settings, the course of relative CRP variations and the CRP ratio, can discriminates, early in the clinical course, survivors from non-survivors." (PMID 25132018, 2014). "The identification of the individual pattern of CRP ratio response to antibiotic therapy appears to be a reflection of the clinical course of infection independently of other possible confounders." (PMID 25132018, 2014). "Materials and Methods: The values of CBC by Cell-DYN 4000 autoanalyzer and serum CRP levels were evaluated in 120 febrile patients with documented infections (n:74 bacterial, n:46 viral) and 22 healthy controls." (PMID 24764729, 2014). "CRP is used to monitor the postoperative course in surgical trauma following orthopaedic implants and to detect prosthetic infection." (PMID 24877114, 2014). "Produced in the liver in response to IL-6, CRP levels rise rapidly during infection and/or inflammation." (PMID 25485262, 2014).
infection (continued). "Several biomarkers of infection, namely C-reactive protein (CRP) and procalcitonin (PCT), have been shown to be useful in the diagnosis of infection in different clinical settings as well as in the assessment of its response to antibiotic therapy." (PMID 25132018, 2014). "This study demonstrates that CRP is accurate for predicting infection in patients with impaired renal function." (PMID 25407928, 2014). "CRP induces innate immune response to infection and/or tissue injury, since CRP activates complement directly, via alternative pathway, and indirectly, via CRP-CFH interaction, which improve CFH ability to inhibit complement." (PMID 25214719, 2014). "Some studies have found that PCT is a more accurate marker for predicting infection than CRP in patients with impaired renal function as well as in those with normal renal function." (PMID 25407928, 2014). "The best cutoff value for diagnosing infection in patients with impaired renal function (group II) was 3.08 mg/dL for CRP and 1.1 ng/mL for PCT." (PMID 25407928, 2014). "Laboratory infection parameters (CRP, WBC), pulmonary imaging LRTI findings and antibiotic use were similar among virus groups." (PMID 25491885, 2014). "Serum CRP level is closely related with the clinical response to therapy and is therefore the preferred marker of the course of infection." (PMID 24767169, 2014). "We observed that the PCT capacity for infection identification is significantly higher than for CRP." (PMID 24903083, 2014). "Babies withmothers showing positive vaginal culture were screened for infection using completeblood count /blood culture (B/C) and C-reactive protein (CRP)." (PMID 24520495, 2014). "PhoPQ, CRP, and Fis fine-tune these global inputs to precisely control the dosage of HlyE, but also the time in the infection cycle in which this gene is expressed." (PMID 24885225, 2014). "In the present study, we evaluated the differential diagnostic value of PCT for infectious SIRS after cardiac surgery and compared PCT with the two most traditional markers of infection, the C-reactive protein (CRP) and white blood cell (WBC)." (PMID 25960877, 2014). "A CRP concentration > 5.0 mg/dl at the D6 was predictive of infection with a sensitivity of 85% and a specificity of 62% (positive likelihood ratio 2.2, negative likelihood ratio 0.2)." (PMID 25132018, 2014). "Under chronic activation of the immune system, immediate responses to infections such as increases in CRP concentrations can become maladaptive in the long term." (PMID 24603645, 2014). "The CRP levels predicted the infection in general one-day earlier, since the mean of postoperative infection occurred on POD7." (PMID 25132018, 2014). "In a separate assessment of preterm and term births, prematures with infection presented significantly lower expression of CRP." (PMID 24659848, 2014). "Many previous studies show that CRP is a difficult biomarker on which to rely solely in diagnosing different kinds of infections, due to the known delay in CRP response." (PMID 25027551, 2014). "C-reactive protein (CRP) and procalcitonin (PCT) levels are known to correlate with the overall extent of infection and higher levels of both have both been linked to higher incidences of organ injury and death in the critically ill." (PMID 24484547, 2014). "Cases with congenital malformation, ascending infection, and perinatal anoxia showed increased IL-6, CRP, and TNF-α, respectively." (PMID 24659848, 2014). "The aim of this study is to evaluate the clinical relevance of PCT compared to CRP as an infection marker based on difference in renal function." (PMID 25407928, 2014). "The C-reactive protein has both anti-inflammatory and proinflammatory effects during infection, since it mediates the elimination of pathogens, despite also inhibiting the interaction between endothelial cells and leukocytes." (PMID 25614712, 2014).
infection (continued). "After resolution of infection complication, CRP decreased again reaching at POD12 values close to those of non-infected patients." (PMID 25132018, 2014). "The association between CRP and PCT levels and the severity of infection in patients with impaired renal function (group II) was also analyzed." (PMID 25407928, 2014). "The AUC for the diagnosis of infection versus non-infection was 0.819 (95% CI 0.782, 0.856) for CRP and 0.831 (95% CI 0.795, 0.866) for PCT." (PMID 25407928, 2014). "In tests conducted by another center, high erythrocyte sedimentation rate (ESR) and C-reactive protein (CRP) values had been detected, and for evaluation she was referred to our hospital with malignity and infection prediagnoses." (PMID 24523978, 2014). "Conversely, in 67.9% and 54.5% of the patients, the CRP levels declined from their raised value after three and four days of institution of antimicrobial therapy, respectively, indicating a correlation between the CRP level and the incidence of infection." (PMID 23634180, 2013). "SAA has been suggested as a more sensitive indicator of inflammation than CRP, and serum levels increase by 1000-fold in response to infection." (PMID 24327799, 2013). "Increased CRP concentrations in a heterogeneous population on the ICU have been associated with organ failure, prolonged ICU stay, high infection rates and mortality rates." (PMID 23409097, 2013). "Measurement of CRP is also a useful test in the diagnosis of infection after total knee arthroplasty and septic arthritis in children." (PMID 23452411, 2013). "We conclude that the IG count displays superior discriminative power for infection over CRP, LBP and IL-6, particularly within the decisive first 48 hours after the onset of SIRS." (PMID 23398965, 2013). "The CRP ratio, already at day 2 but certainly at day 4, is more predictive of infection and/or adequate antibiotherapy than individual values." (PMID 24286072, 2013). "Organisms isolated from positive blood cultures in patients with confirmed infections (N = 38) and CRP persistently <10 mg/L." (PMID 24244325, 2013). "CRP is one of several acute-phase proteins (APPs) that can be used to assess the innate immune system’s systemic response to infection, inflammation or trauma." (PMID 23452411, 2013). "C-reactive protein (CRP), an acute-phase protein, is a highly sensitive systemic marker of inflammation, infection, and tissue damage." (PMID 24073339, 2013). "The cardiovascular risk seemed to be highest among those who showed both evidence of some chronic, low-grade infection, and elevated CRP levels." (PMID 24267704, 2013). "The C-reactive protein levels on the first and second postoperative days were significantly greater in the infection group (p = 0.02 and p = 0.05, respectively)." (PMID 23819455, 2013). "Increase in the mRNA levels of ICAM-1, VCAM-1 and MCP-1 was observed on addition of CRP or high glucose and infection with IGFBP-3 significantly decreased these levels." (PMID 23383064, 2013). "In contrast, patients infected with coagulase-negative staphylococci, displayed considerably milder signs of infection (low body temperature and CRP) than those infected with other organisms." (PMID 23369129, 2013). "Seventy-eight percent of attendees considered physical examination to be an appropriate method of detecting infection, while only 63% considered biochemical examination (CRP) to be an appropriate method, and 40% considered culture to be appropriate." (PMID 23570330, 2013). "For this purpose, we suggest using an ELISA-based measurement of plasma CRP levels as the most sensitive and optimal parameter to determine the presence of a developing implant infection." (PMID 24188807, 2013). "These patients also frequently present with impaired ability to increase plasma C-reactive protein and to mount fever in response to infection, with spontaneous improvement in adolescence." (PMID 22996269, 2013).